EXTL3 (exostosin like glycosyltransferase 3)
Description:
Glycosyltransferase which regulates the biosynthesis of heparan sulfate (HS). Initiates HS synthesis by transferring the first N-acetyl-alpha-D-glucosamine (alpha-GlcNAc) residue (GlcNAcT-I activity) to the tetrasaccharide linker (GlcA-Gal-Gal-Xyl-)Ser core linker. May also transfer alpha-GlcNAc residues during HS elongation (GlcNAcT-II activity). Lacks glucuronyl transferase II (GlcAT-II) activity. Important for both skeletal development and hematopoiesis, through the formation of HS proteoglycans (HSPGs). Through the synthesis of HS, regulates postnatal pancreatic islet maturation and insulin secretion (By similarity). Receptor for REG3A, REG3B and REG3G, induces the activation of downstream signaling pathways such as PI3K-AKT or RAS-RAF-MEK-ERK signaling pathway. Required for the function of REG3A in regulating keratinocyte proliferation and differentiation. Required for the inhibition of skin inflammation mediated by REG3A through the activation of PI3K-AKT-STAT3 pathway. Required for the function of REG3A and REG3G in glucose tolerance in pancreas. Expressed in microglia, is activated by nociceptor-derived REG3G in response to endotoxins, leading to the inhibition of kynurenine pathway to prevent endotoxic death (By similarity).
Synonyms: EXTL1L; EXTR1; botv; REGR; ISDNA; RPR
Tractability: Small molecule: a structure with a bound ligand is known. Antibody: UniProt places it where antibodies can reach, with high confidence; its Gene Ontology location is reachable by antibodies, with high confidence; UniProt predicts a signal peptide or a membrane-spanning region. PROTAC: ubiquitination databases record sites on it; its protein half-life has been measured.
Gene: Protein-coding gene on chromosome 8 (28,600,469 to 28,756,561, forward strand). Ensembl gene ENSG00000012232.
Subcellular location: Endoplasmic reticulum membrane; Golgi apparatus; Cell membrane; Nucleus
Pathways (Reactome):
Cellular responses to stimuli: XBP1(S) activates chaperone genes
Metabolism: HS-GAG biosynthesis
Gene Ontology:
Molecular function: glucuronyl-galactosyl-proteoglycan 4-alpha-N-acetylglucosaminyltransferase activity; glycosyltransferase activity; magnesium ion binding; protein binding; protein-hormone receptor activity; acetylglucosaminyltransferase activity
Biological process: heparan sulfate proteoglycan biosynthetic process; negative regulation of inflammatory response to wounding; negative regulation of keratinocyte differentiation; positive regulation of keratinocyte proliferation; positive regulation of phosphatidylinositol 3-kinase/protein kinase B signal transduction; negative regulation of cytokine production involved in inflammatory response; negative regulation of inflammatory response; positive regulation of detection of glucose; glycoprotein biosynthetic process; positive regulation of cell growth
Cellular component: endoplasmic reticulum; Golgi apparatus; nucleus; plasma membrane; endoplasmic reticulum membrane; Golgi membrane; membrane
Genetic constraint (gnomAD): Loss-of-function variants: 27 observed, 72.83 expected, observed/expected ratio (o/e) 0.37, 90% interval 0.27 to 0.51. The upper end of that interval is the gene's LOEUF score, 0.51, which puts it in group 2 of 6, group 1 being the genes least tolerant of losing a copy. Missense variants: 1,003 observed, 1,292.8 expected, observed/expected ratio (o/e) 0.78, 90% interval 0.74 to 0.82. Synonymous variants: 511 observed, 524.74 expected, observed/expected ratio (o/e) 0.97, 90% interval 0.9 to 1.05.
Gene-disease validity (ClinGen):
ClinGen rates the evidence that EXTL3 causes each of these diseases.
immunoskeletal dysplasia with neurodevelopmental abnormalities (autosomal recessive): Moderate.
Homologues: Orthologues: chimpanzee EXTL3 (99% identical), macaque EXTL3 (99% identical), rabbit EXTL3 (98% identical), mouse Extl3 (97% identical), pig EXTL3 (97% identical), guinea pig EXTL3 (97% identical), dog EXTL3 (96% identical), rat Extl3 (95% identical), tropical clawed frog extl3 (88% identical), zebrafish extl3 (83% identical), Drosophila melanogaster botv (52% identical), Caenorhabditis elegans rib-2 (34% identical). Paralogues in human: EXT2 (28% identical), EXT1 (24% identical), EXTL1 (20% identical), EXTL2 (11% identical).
Diseases named in the same sentence as EXTL3 in open-access papers:
EXTL3 is named in the same sentence as 39 diseases in open-access papers, as found by Europe PMC text mining. Sharing a sentence is not in itself a finding about the gene and the disease. The quoted sentences say what the papers report.
immune deficiency (6 papers, 2019 to 2024). "Exostosin like glycosyltransferase 3 (EXTL3) had been reported to be associated with immune deficiency and play prognostic roles in various cancers." (PMID 35818069, 2022). "Biallelic hypomorphic mutations in EXTL3 have been described in a rare syndromic immunodeficiency characterised by skeletal dysplasia, and more variably by neurodevelopmental delay and T cell lymphopaenia." (PMID 33257998, 2021). "In humans, a mutation affected the EXTL3 gene causing skeletal dysplasia, immune deficiency and development delay." (PMID 31171566, 2019). "The pathogenesis of immunodeficiency in EXTL3 deficiency appears to be multifactorial." (PMID 33257998, 2021). "Consistently, EXTL3-CDG immunodeficiency was shown to majorly derive from defects in early T cell development." (PMID 38550576, 2024). "Moreover, as we had described previously, EXTL3 belonged to the EXT family, playing vital roles in predicting various cancers’ prognosis and immune deficiency." (PMID 35818069, 2022). "EXTL3- and PGM3-CDG are the CDG included in the category of combined immunodeficiencies with syndromic features, presenting variable immunophenotypes ranging from isolated infections to severe immunodeficiency, including neurodevelopmental and skeletal defects." (PMID 38550576, 2024).
colon carcinoma (2 papers, 2017 to 2025). "In 2009, Italian researchers described a 31-year-old man with juvenile-onset colon carcinoma harboring a missense variant in EXTL3." (PMID 41441317, 2025). "In a high percentage of the colon cancers of the mucinous type, EXTL3 is down-regulated by promoter methylation." (PMID 28481247, 2017). "On the contrary, hypermethylation of EXTL3 promoter has never been reported in non-mucinous colon cancers." (PMID 28481247, 2017).
developmental delay (2 papers, 2018 to 2020). "For example, EXTL3 and CHSY1 mutations, which affect heparan sulfate and chondroitin sulfate synthesis, respectively, cause developmental delay and intellectual disabilities." (PMID 32001716, 2020).
endometriosis (2 papers, 2019 to 2020). The growth of functional endometrial tissue in anatomic sites outside the uterine body. "The involvement of EXTL3 in endometriosis, a benign chronic condition characterized by the existence of endometrial-like stroma and glandular tissue in extrauterine locations, was recently reported." (PMID 32843889, 2020). "Since EXTL3 is involved in HS synthesis, we measured antibody titers to EXTL3 and found increased titers in endometriosis group." (PMID 31467315, 2019). "In conclusion, we have detected EXTL3 expression in endometrial tissue as well as endometriosis lesions." (PMID 31467315, 2019). "The fact that colony formation required the presence of both the overexpressed EXTL3 and endometriosis serum, indicates a positive interaction." (PMID 31467315, 2019). "We found increased antibody titers to EXTL3 peptide 3 in endometriosis group (E) compared to endometriosis free (N) group." (PMID 31467315, 2019). "We have studied the role of EXTL3 (exostosin-like 3) in endometriosis and found that it is expressed in endometrial tissue as well as endometriosis lesions." (PMID 31467315, 2019). "We have found that serum from endometriosis patients contains a factor or factors, which interact with EXTL3 resulting in strongly increased colony formation in regenerating cell culture." (PMID 31467315, 2019). "We found increased anti-EXTL3 antibodies in endometriosis patients’ sera." (PMID 31467315, 2019). "We also found increased anti-EXTL3 antibodies in endometriosis patients’ sera." (PMID 31467315, 2019). "Therefore, EXTL3 was chosen as a plausible study candidate for a target molecule in endometriosis; a disorder involving excessive cellular proliferation." (PMID 31467315, 2019). "We had previously found EXTL3 antibodies in endometriosis serum." (PMID 31467315, 2019). "However, cell surface HS synthesized by EXTL3 may regulate the cell entry of viruses, potentially contributing to the pathogenesis of endometriosis." (PMID 32843889, 2020). "In the following experiment, using eutopic endometrial stromal cells from a different donor (E305, who had infertility, but no endometriosis), the cells were transfected with wtEXTL3-EGFP, EXTL3-ΔC-EGFP, and EGFP plasmids and cultured with 5% human serum from an endometriosis patient." (PMID 31467315, 2019). "We conclude that EXTL3 expression in endometrium is ubiquitous in patients and healthy individuals and not different in eutopic and endometriosis samples." (PMID 31467315, 2019). "Although REG proteins were not examined in that study, EXTL3 may play a role in endometriosis as a membrane signaling molecule that interacts with these ligands." (PMID 32843889, 2020).
gastric cancer (2 papers, 2022). A primary or metastatic malignant neoplasm involving the stomach. "For this purpose, we have established glycoengineered gastric cancer cell models by knocking out either EXTL2 or EXTL3 from MKN74 cells and evaluated the impact of both glycosyltransferase KOs over GAG biosynthesis." (PMID 36181793, 2022). "To uncover the impact of specific GAGosylation profiles from EXTL2 KO and EXTL3 KO gastric cancer cells in the activation of RTKs, we screened the phosphorylation state of multiple RTKs using a phospho array." (PMID 36181793, 2022). "In this work, we have evaluated the roles of EXTL2 and EXTL3 in HS biosynthesis in gastric cancer." (PMID 36181793, 2022). "EXTL3 promoter methylation could reduce EXTL3 expression, resulting in the loss of heparan sulfate in colorectal cancer and the ubiquitous expression of regenerating gene (REG) Iα receptor EXTL3 was found in gastric cancer vessel cells and tumor cells." (PMID 35818069, 2022). "In the present study, we disclosed the regulatory roles of EXTL2 and EXTL3 in GAG and HSPG biosynthetic pathways, in the context of gastric cancer, and evaluated the impact of the resulting altered GAGosylation in cancer cells’ motility and signaling features." (PMID 36181793, 2022). "In this study, we established glycoengineered gastric cancer cell models lacking either exostosin-like glycosyltransferase 2 (EXTL2) or EXTL3 and revealed their regulatory roles in both HS and chondroitin sulfate (CS) biosynthesis and structural features." (PMID 36181793, 2022). "We showed that EXTL3 is key for initiating the synthesis of HS chains in detriment of CS biosynthesis, intervening in the fine-tuned balance of the HS/CS ratio in cells, while EXTL2 functions as a negative regulator of HS biosynthesis, with impact over the glycoproteome of gastric cancer cells." (PMID 36181793, 2022).
glioma (2 papers, 2022). A benign or malignant brain and spinal cord tumor that arises from glial cells (astrocytes, oligodendrocytes, ependymal cells). "We also validated the expression of non-coding RNA that targets MCM4 and found that EXTL3-AS1was highly expressed, and miR-24-3p was down-regulated in glioma cell lines, respectively." (PMID 36465369, 2022).
psoriasis (2 papers, 2019 to 2020). An autoimmune condition characterized by red, well-delineated plaques with silvery scales that are usually on the extensor surfaces and scalp. "In the skin of psoriasis patients, HIP/PAP is highly expressed via IL-17 and promotes keratinocyte proliferation through engagement of exostosin-like 3 (EXTL3) and activation of the PI3K-AKT signaling pathway." (PMID 32508838, 2020).
chronic pancreatitis (1 paper, 2014). A chronic inflammatory process causing damage and fibrosis of the pancreatic parenchyma. "Expression of EXTL3, putative REG Iα receptor, was observed in beta cells of FT1DM, chronic pancreatitis, type 2 diabetes and non-diabetic control." (PMID 24759849, 2014).
diabetes (1 paper, 2015). "ISC activation is inhibited by Reg1, which acts primarily through EXTL3 to prevent diabetes-induced activation of the ISC fibrotic phenotype." (PMID 26496027, 2015).
disc degeneration (1 paper, 2019). "Our results also showed that several enzymes that catalyze the biosynthesis of sulfated glycosaminoglycans (GAGs) of proteoglycans, including CHST1, EXTL3 and SLC26A2, were differentially methylated in the advanced stage of human disc degeneration compared to those in the early stage." (PMID 31513634, 2019).
exostoses (1 paper, 2020). "Considering that dominant mutations in EXT1 and EXT2 genes cause hereditary multiple exostoses and the EXTL1 gene is expressed at very low levels in brain cells, EXTL2 and EXTL3 represent the most promising candidates in this pathway for SRT." (PMID 32121121, 2020).
insulinoma (1 paper, 2020). "The overexpression of Extl3 in the rat insulinoma-derived β-cell line RINm5F increased its cell proliferation in response to a Reg1 protein, suggesting that Reg1 protein-dependent signaling is enhanced by the strongly expressed receptor Extl3." (PMID 32843889, 2020).
pancreatitis (1 paper, 2024). Inflammation of the pancreas. "Mechanistically, Reg4 mediates its function in pancreatitis potentially via binding its receptor exostosin-like glycosyltransferase 3 (Extl3)." (PMID 38769308, 2024). "We thus suggest Extl3 may functions as the receptor for Reg4 and mediates the activation of downstream signaling proteins during pancreatitis." (PMID 38769308, 2024). "EXTL3 may functions as the receptor for REG4 during pancreatitis." (PMID 38769308, 2024).
primary immunodeficiencies (1 paper, 2018). "Furthermore, several heterozygous variants were identified in genes associated with known primary immunodeficiencies that are inherited in an autosomal recessive manner, such as LYST, LRBA, RAG1, EXTL3, and STX11 (Group 4)." (PMID 30723478, 2018).
syphilis (1 paper, 2018). A contagious bacterial infection caused by the spirochete Treponema pallidum. "EXTL3, involved in the heparan sulfate biosynthesis pathway and previously associated with syphilis, was expressed in both patients with jaw claudication and fatigue." (PMID 30037347, 2018).
triple-negative breast carcinoma (1 paper, 2018). An invasive breast carcinoma which is negative for expression of estrogen receptor (ER), progesterone receptor (PR), and human epidermal growth factor receptor 2 (HER2). "The two triple-negative breast carcinoma cell lines exhibited a similar pattern of EXT gene expression with significantly increased expression of EXTL2 and reduced expression of EXTL3." (PMID 30054430, 2018).
viral infection (1 paper, 2021). "Thus, direct targeting of the key enzyme EXTL3 of the HS biosynthesis pathway proved the importance of HS as a host factor involved in viral infection of low affinity variants even in the presence of DAG1 and for high affinity variants in the absence of functional DAG1." (PMID 34648606, 2021).
cancer (7 papers, 2018 to 2026). A tumor composed of atypical neoplastic, often pleomorphic cells that invade other tissues. "Conversely, EXTL1, EXTL2, and EXTL3 showed inconsistent and context-specific expression patterns across cancers." (PMID 41438585, 2026). "Our findings uncover the biosynthetic roles of EXTL2 and EXTL3 in the regulation of cancer cell GAGosylation and proteoglycans expression and unravel the functional consequences of aberrant HS/CS balance in cellular malignant features." (PMID 36181793, 2022). "Currently, there is very limited knowledge regarding the expression and impact of EXTL2 and EXTL3 in the context of cancer pathologies." (PMID 36181793, 2022). "To characterize HS and CS glycan structures from EXTL2 KO and EXTL3 KO glycoengineered cancer cell lines, we isolated and purified cellular GAGs and performed HS and CS disaccharide analyses using reversed-phase ion pair HPLC (RPIP-HPLC)." (PMID 36181793, 2022). "The expression of EXT2 and EXTL3 was reduced in all cancer cell lines whereas EXTL2 was down-regulated in MCF7 cells but highly up-regulated in MDA-MB-231, and HCC38." (PMID 30054430, 2018). "Interestingly, the most significantly upregulated genes in Ppm1dT/+ AML (Zbed3, Runx3, Marcks, Extl3, Pcbp4, Igf2bp3, Plch1, and Gdf6) were previously associated with AML and cancer progression." (PMID 37709843, 2023). "To determine the functional impact of altered GAGosylation in cancer cell motility, we performed wound healing assays and evaluated the migration rates of EXTL2 KO and EXTL3 KO cells on fibronectin and collagen IV coated surfaces." (PMID 36181793, 2022).
tumor (5 papers, 2003 to 2024). "Sangerbox website was utilized to assess the relationships between EXTL3 expression and immunity and Tumor Immune Dysfunction and Exclusion (TIDE) dataset was applied to predict immune responses." (PMID 35818069, 2022). "As for tumor microenvironment, EXTL3 expression was also remarkably correlated with ESTIMATEScore, ImmuneScore, StromalScore (all P < 0.001)." (PMID 35818069, 2022). "EXTL3 expression was also revealed to be significantly associated with MSI, immune cells, immune checkpoint molecules, tumor microenvironment and immune cells infiltration." (PMID 35818069, 2022). "In terms of tumor microenvironment, EXTL3 expression was also remarkably correlated with ESTIMATEScore, ImmuneScore, StromalScore." (PMID 35818069, 2022). "All four genes (EXTL2, EXTL3, EXT1, and EXT2) involved in elongation of the backbone of HS chains are significantly >2-fold upregulated in tumor compared to the adjacent benign tissues." (PMID 33585200, 2020). "These genes likely function as downstream effectors of STAT3 in GBM to regulate not only cell proliferation (e.g., GAS7, IGFBP2, MEOX2 and MXI1), and but also tumor-stroma interactions by modulating protein secretion (e.g., ANXA1, ARL4C, EMILIN1, EMP2, EXTL3 and PDIA4)." (PMID 29774125, 2018).
infection (2 papers, 2009 to 2021). The state of being infected such as from the introduction of a foreign agent such as serum, vaccine, antigenic substance or organism. "Although the reduction of HS on the cell surface was not complete, it was sufficient to achieve a similar decrease of infection as observed for knockout of EXTL3." (PMID 34648606, 2021).
neurological disorders (2 papers, 2020 to 2022). "Deleterious missense mutations in the EXTL3 gene can cause a range of developmental and neurological disorders in humans." (PMID 35676258, 2022). "In addition, it will be interesting to examine LAMP2- and HS-related phenotypes in iAs, due to the important role of astrocytes in neurological disorders and the potential of SRT targeting EXTL2 and EXTL3 in iAs." (PMID 32121121, 2020).
Genetic diseases (1 paper, 2020). "Genetic diseases caused by biallelic mutations in the EXTL3 gene were recently reported to result in a neuro-immuno-skeletal dysplasia syndrome." (PMID 32843889, 2020). "Genetic diseases caused by biallelic mutations in the EXTL3 gene have been reported." (PMID 32843889, 2020).
EXTL3 also shares sentences with these, for which no sentence is quoted: skeletal dysplasia (4 papers); immunodeficiency (3); ataxia telangiectasia (1); autism (1); breast carcinoma (1); cartilage-hair hypoplasia (1); colorectal cancer (1); Infertility (1); lung carcinoma (1); meningitis (1); pancreatic ductal adenocarcinoma (1); prostate carcinoma (1); Retinal dysplasia (1); Roifman syndrome (1); Sanfilippo C (1); Schimke immuno-osseous dysplasia (1); type 2 diabetes (1).